RN7SL633P (RNA, 7SL, cytoplasmic 633, pseudogene)
Gene: Miscellaneous RNA gene on chromosome 22 (31,059,989 to 31,060,285, forward strand). Ensembl gene ENSG00000240186.
Homologues: Orthologues: chimpanzee Metazoa_SRP (99% identical), macaque Metazoa_SRP (93% identical). Paralogues in human: RN7SL584P (97% identical), RN7SL400P (97% identical), RN7SL1 (79% identical), RN7SL3 (79% identical), RN7SL2 (78% identical), RN7SL220P (77% identical), RN7SL464P (77% identical), RN7SL127P (76% identical), RN7SL679P (76% identical), RN7SL493P (76% identical), RN7SL769P (76% identical), RN7SL797P (76% identical), and 698 more.